MADCAM1 (mucosal vascular addressin cell adhesion molecule 1)
Diseases named in the same sentence as MADCAM1 in open-access papers (continued):
Sharing a sentence is not in itself a finding about the gene and the disease.
Crohn disease (7 papers, 2018 to 2024). A gastrointestinal disorder characterized by chronic inflammation involving all layers of the intestinal wall, noncaseating granulomas affecting the intestinal wall and regional lymph nodes, and transmural fibrosis. "Research has shown that MAdCAM-1 is overexpressed in the sites involved with inflammatory processes in persons with Crohn’s disease (CD) and the interaction between α4β7 integrin and MAdCAM-1 is possibly even responsible for the state of chronic inflammation observed in intestinal diseases." (PMID 34827121, 2021). "The mention of a clinical trial involving an anti-MadCam1 drug and its impact on CCR9 expression in active Crohn’s disease (aCD) patients is significant." (PMID 37893204, 2023). "For instance, the targeted microbubbles using antibodies against mucosal addressin cell adhesion molecule-1 (MAdCAM-1) or vascular adhesion molecule-1 (VCAM-1) were useful in the ultrasound imaging and gene therapy in crohn’s disease." (PMID 33066531, 2020). "A phase II study of fully human antibody towards MAdCAM-1 showed induction of remission and mucosal healing after 12 weeks in patients with ulcerative colitis but not with Crohn’s disease, probably due to an inflammatory change that extends through the entire bowel wall." (PMID 36010364, 2022).
ulcerative colitis (6 papers, 2005 to 2024). An inflammatory bowel disease involving the mucosal surface of the large intestine and rectum. "Lastly, sodium butyrate pre- and co-treatment attenuated the direct effects of ethanol and LPS on MAdCAM-1 induction in the HIMECs from a patient with ulcerative colitis." (PMID 38338944, 2024). "PNAd and MAdCAM-1 addressins on venules are of importance in T-cell homing and potential therapeutic targets in ulcerative colitis (UC)." (PMID 32268498, 2020).
diabetes (5 papers, 2018 to 2024). "Furthermore, NOD mice treated at an early age with an antibody blocking the mucosal addressin cell adhesion molecule-1 (MAdCAM-1) were almost completely protected from diabetes at 32-weeks old (9% diabetic compared to 80% in the control group)." (PMID 36059452, 2022). "Furthermore, antibodies blocking either α4β7-integrin or its ligand, the mucosal addressin cell adhesion molecule (MadCAM-1), prevent diabetes in NOD mice." (PMID 30662436, 2018). "To test the hypothesis that temporarily blocking MAdCAM-1 during the critical window for priming of naive autoreactive T cells would inhibit the development of islet inflammation and diabetes, we gave 3-week-old NOD mice one intraperitoneal (ip) injection of anti-MAdCAM-1 or isotype control mAb." (PMID 39518902, 2024). "In addition, antibodies blocking α4β7 or MadCAM-1, prevent diabetes in NOD mice." (PMID 30662436, 2018). "Thus, we assume that the Treg cells in islets after MAdCAM-1 blockade may exert direct and/or indirect effects on autoreactive effector/memory T cells in the pancreas and thus prevent the progression of insulitis and the development of diabetes." (PMID 39518902, 2024). "Transient blockade of MAdCAM-1 in 3-week-old NOD mice led to increased numbers of Treg cells in inflamed pancreata and to long-term protection from the development of diabetes." (PMID 39518902, 2024). "Although blockade of MAdCAM-1 failed to prevent islet inflammation, none of 10 mice treated with anti-MAdCAM-1 mAb developed diabetes within 1 year of treatment." (PMID 39518902, 2024). "Our results thus far indicate that transient blockade of MAdCAM-1 prevents the development of diabetes but not activation of naive autoreactive T cells in pan-LNs or development of islet inflammation." (PMID 39518902, 2024). "It has been reported that PNAd+ MAdCAM-1+ HEV-like vascular structure develops ectopically in the pancreas of non-obese diabetes model NOD mice due to lymphocyte infiltration." (PMID 36045707, 2022). "Thus, temporary inhibition of MAdCAM-1 during the initiation stage of the autoimmune response provides significant, long-lasting protection from diabetes but not from islet inflammation." (PMID 39518902, 2024).
melanoma (4 papers, 2014 to 2020). A malignant, usually aggressive tumor composed of atypical, neoplastic melanocytes. "Previous study suggested that TRIM59 loss in M2 macrophages promotes melanoma migration and invasion by upregulating MMP-9 and Madcam1." (PMID 32867817, 2020). "Our study showed that TNF-α promoted the expression of MMP-9 and Madcam1 in melanoma cells, which contributed to melanoma growth and metastasis." (PMID 31600735, 2019). "Transcriptome analysis revealed significant upregulation of MMP-9 and Madcam1 in melanoma cells exposed to TRIM59-/--M2 CM." (PMID 31600735, 2019). "Independent knockdown of either MMP-9 or Madcam1 by shRNA in melanoma cells inhibited EMT and invasion induced by TRIM59-/--M2 macrophage CM, and attenuated the growth of subcutaneous B16-F10 tumors and reduced lung metastasis burden in TRIM59-CKO-mice." (PMID 31600735, 2019). "MAdCAM-1 has also been detected outside the endothelial lineage on follicular DCs, fibroblasts and melanoma cells." (PMID 24830732, 2014). "In our study, TRIM59-/ -macrophages mediated upregulation of the PI3K and ERK signaling pathways in B16 melanoma cells, promoting MMP-9 and Madcam1 expression and stimulating migration and invasion in vitro, as well as tumorigenesis, EMT, and metastasis in an in vivo tumor model." (PMID 31600735, 2019). "Because knockdown of MMP-9 did not alter Madcam1 protein levels, and Madcam1 silencing did not affect MMP-9 protein expression, we conclude that the effects were independent, and that both proteins are needed for metastatic dissemination of melanoma cells." (PMID 31600735, 2019).
colon tumor (3 papers, 2012 to 2022). "Our present results extend these findings to another major type of gastrointestinal tumors, showing that also in colon tumors there are decreased frequencies of CD4+ conventional T cells and Treg expressing α4β7 and a concomitant decrease in MAdCAM-1 expression on the blood vessels." (PMID 22319577, 2012).
experimental autoimmune encephalomyelitis (3 papers, 2011 to 2022). An autoimmune demyelinating disease of the central nervous system that is produced experimentally in animals by the injection of homogenized brain or spinal cord in Freund's adjuvant. "Using the experimental autoimmune encephalomyelitis model of MS, we show that MAdCAM-1-deficient (MAdCAM-1-KO) mice are less susceptible to actively MOG35−55-induced disease." (PMID 31114574, 2019). "Ultrastructural studies in an experimental autoimmune encephalomyelitis model revealed polar localization of ICAM-1, VCAM-1, and MAdCAM-1 on the apical surface of choroid plexus epithelial cells and their complete absence on the fenestrated endothelial cells within the choroid plexus parenchyma." (PMID 21592385, 2011). "Furthermore, endothelial overexpression of mucosal vascular addressin cell-adhesion molecule 1 (MAdCAM-1, the counter-receptor of α4β7-integrin) does not correlate with experimental autoimmune encephalomyelitis (EAE) severity." (PMID 35008929, 2022).
gastric cancer (3 papers, 2012 to 2025). A primary or metastatic malignant neoplasm involving the stomach. "In gastric cancer, a unique endothelial cell subtype called Venes-1 is characterized by the expression of IL-33 and MADCAM1." (PMID 41303611, 2025). "Previously, we have shown that gastric cancer patients have a decreased expression of MAdCAM-1 on tumor blood vessels, and that this was accompanied by fewer α4β7+ LPL in tumor mucosa compared to unaffected mucosa." (PMID 22319577, 2012).
multiple myeloma (3 papers, 2021 to 2025). "Sialyltransferase inhibitor may suppress relationships between E-selectin, VCAM1, and MADCAM1, thereby prolonging survival time of multiple myeloma patients." (PMID 34249967, 2021).
primary sclerosing cholangitis (3 papers, 2007 to 2024). "The α4β7/MAdCAM-1 axis is also implicated in promoting hepatic inflammation in chronic inflammatory liver diseases and primary sclerosing cholangitis (PSC), and upregulation of MAdCAM-1 expression is reported in the liver of most CLD patients." (PMID 38727292, 2024).
bladder cancer (2 papers, 2024 to 2025). "Moreover, low serum levels of soluble MAdCAM-1 were correlated with poor prognosis in independent cohorts of lung, kidney, and bladder cancer patients, suggesting that the MAdCAM-1–α4β7 axis could be a targetable gut immune checkpoint in cancer immunosurveillance." (PMID 41247642, 2025).
Chronic colitis (2 papers, 2022). A chronic inflammatory disease of the large intestine (colon, cecum and rectum). "Here, we examined the role of α4β7 integrin during chronic colitis using IL-10−/− mice, β7-deficient IL-10−/−, IgA-deficient IL-10−/− mice, and antibody blockade of MAdCAM-1." (PMID 34433904, 2022). "Thus, in order to dissect the roles of αEβ7 and α4β7 during chronic colitis, we treated IL-10−/− mice with an antibody against the α4β7-specific ligand, MAdCAM-1 (MECA-367)." (PMID 34433904, 2022). "MAdCAM-1 increased both at acute and chronic colitis, suggesting lymphocytes of the adaptive immune system could account for the main damage factors of the bowel in this model, while Sodium Houttuyfonate combined with Matrine could alleviate this inflammatory damage." (PMID 35844499, 2022). "Interestingly, MAdCAM-1 increased both at acute and chronic colitis, suggesting that lymphocytes of the adaptive immune system might be the main damage factors of the bowel in this model." (PMID 35844499, 2022).
Cirrhosis (2 papers, 2020 to 2025). A chronic disorder of the liver in which liver tissue becomes scarred and is partially replaced by regenerative nodules and fibrotic tissue resulting in loss of liver function. "Mice with CCL4-induced cirrhosis also exhibited greater aggregation of α4β7+ T cells and higher expression of Itga4, Itgb7, and MADCAM-1." (PMID 41301753, 2025). "showing that hepatic MAdCAM-1 mRNA expression is upregulated in cirrhosis, so long-term PSC." (PMID 32743534, 2020).
colonic disease (2 papers, 2018 to 2023). "The lack of clinical efficacy observed with PF-00547659 in the OPERA study has led to the suggestion that MAdCAM-1 blockade may only be effective in superficial colonic disease, ie UC." (PMID 28961803, 2018). "The absence of efficiency observed in this study suggests that MAdCAM-1 blockade might only be effective in superficial colonic disease, as there have been studies on the efficacy of this drug in UC with clinically and statistically significant results, inviting further research on this topic." (PMID 38004446, 2023).
colorectal cancer (2 papers, 2018 to 2020). A primary or metastatic malignant neoplasm that affects the colon or rectum. "Variants in the ZFYVE26 gene have been associated with colorectal cancer, variants in the MADCAM1 gene have been associated with multiple sclerosis, and variants in the FAM20C gene have been associated with development of Raine syndrome in humans." (PMID 33195511, 2020). "This correlates with human data showing lower MAdCAM-1 expression and disease-free survival in colorectal cancer patients." (PMID 30235302, 2018).
Hepatic fibrosis (2 papers, 2023 to 2024). The presence of excessive fibrous connective tissue in the liver. "Treatment with MAdCAM-1 mAb decreased hepatic fibrosis, indicated by marked decrease in the deposition of hepatic collagen in the Sirius Red-stained liver tissue sections." (PMID 38727292, 2024). "We demonstrate that blocking antibodies against α4β7 and MAdCAM-1 that reduce recruitment of α4β7+ CD8 T cells to the liver improves CCL4-induced hepatic fibrosis." (PMID 38727292, 2024). "Furthermore, we demonstrate that treatment with MAdCAM-1 mAb also protects mice from CCl4-induced liver fibrosis by blocking α4β7+ T cell recruitment to the liver." (PMID 38727292, 2024). "In conclusion, our findings shed light on the crucial role of the α4β7/MAdCAM-1 axis in regulating hepatic fibrosis and highlight the potential therapeutic strategy of utilizing mAbs targeting integrin α4β7 or MAdCAM-1 to treat inflammation and fibrosis in CLD." (PMID 38727292, 2024). "The findings suggest that α4β7+ T cells play a critical role in promoting hepatic fibrosis progression, and mAb-mediated blockade of α4β7 or MAdCAM-1 represents a promising therapeutic strategy for slowing hepatic fibrosis progression in chronic liver diseases." (PMID 38727292, 2024). "This selectivity in blocking effector CD4 T cell recruitment while preserving the presence of immunomodulatory Tregs may have played a crucial role in the effectiveness of α4β7 and MAdCAM-1 mAbs in suppressing hepatic fibrosis." (PMID 38727292, 2024). "Despite strong evidence suggesting that the α4β7/MAdCAM-1 axis is influential in CLD, the role of α4β7/MAdCAM-1 axis in promoting hepatic fibrosis progression remains poorly delineated." (PMID 38727292, 2024). "Improvement in liver fibrosis was associated with a significant decrease in the infiltration of α4β7+ CD4 and CD8 T cells, suggesting that α4β7/MAdCAM-1 axis regulates both CD4 and CD8 T cell recruitment to the fibrotic liver, and α4β7+ T cells promote hepatic fibrosis progression." (PMID 38727292, 2024).
Hepatitis (2 papers, 2020 to 2024). Inflammation of the liver. "Additionally, whole-body knockout mice lacking MAdCAM-1 or β7 have been shown to be protected from concavalin A-induced hepatitis." (PMID 38727292, 2024).
intestinal inflammation (2 papers, 2015 to 2023). "Specially, regulation of rolling of TEM cells on the MadCAM-1 by Rap1-GDP restricted their homing to the colon, which contributed to prevention of T-cell-dependent intestinal inflammation." (PMID 26634692, 2015).
multiple sclerosis (2 papers, 2011 to 2020). A progressive autoimmune disorder affecting the central nervous system resulting in demyelination. "Human MADCAM-1 mRNA transcripts are expressed in the brain and abnormal elevation of MADCAM-1 has been described in patients with multiple sclerosis." (PMID 21658278, 2011).
primary biliary cholangitis (2 papers, 2020 to 2025). Primary biliary cholangitis (PBC) is a chronic and slowly progressive cholestatic liver disease of autoimmune etiology characterized by injury of the intrahepatic bile ducts that may eventually lead to liver failure. "In addition, MAdCAM-1 is upregulated in different inflammatory disorders in both gut and liver, including IBD but also PSC, primary biliary cholangitis (PBC), and hepatitis C virus (HCV) [6,]." (PMID 32743534, 2020).
psoriasis (2 papers, 2021 to 2022). An autoimmune condition characterized by red, well-delineated plaques with silvery scales that are usually on the extensor surfaces and scalp. "As for levels of the proteins evaluated in relation to the PASI subgroups, no statistical differences were found between both of them, except for the downward trend of MAdCAM-1 in patients with mild psoriasis (PASI I) as compared to the controls (p = 0.12)." (PMID 34827121, 2021). "In a recently published paper, we demonstrated that mucosal addressin cell adhesion molecule-1 (MAdCAM-1) might play a role as an inflammation indicator in psoriasis, but also exerts a beneficial impact on the lipid profile in LP." (PMID 36144281, 2022). "MAdCAM-1 and ITGB7 molecules and their serum levels in patients with psoriasis and lichen planus have never been studied before; therefore, we are the first trying to analyze it in order to develop the current state of knowledge on psoriasis and lichen planus to better help patients." (PMID 34827121, 2021).
Sepsis (2 papers, 2022 to 2025). Sepsis is defined as life-threatening organ dysfunction caused by a dysregulated host response to infection. "Additionally, treating AKI in the setting of sepsis with antibiotics may alter the microbiome, which has been shown to dampen ICI effectiveness by down‐regulating mucosal addressin cell adhesion molecule 1 (MAdCAM‐1)." (PMID 40719750, 2025).
Stroke (2 papers, 2017 to 2023). Sudden impairment of blood flow to a part of the brain due to occlusion or rupture of an artery to the brain. "At 1 day after stroke, Vcam1, Madcam1, and Cx3cl1 showed upregulation (Vcam1, Madcam1, and Cx3cl1), and this change of Cx3cl1 expression remained 2 days later (Cx3cl1)." (PMID 28754163, 2017). "Choroid plexus tissues were collected and analyzed for Vcam1, Madcam1, Cx3cl1, Ccl2, Nt5e, and Ifnγ expression at different timepoints after stroke using qPCR." (PMID 28754163, 2017).
acute pancreatitis (1 paper, 2021). An acute inflammatory process that leads to necrosis of the pancreatic parenchyma. "The expression of MAdCAM-1 on pancreatic vascular endothelium has been recorded in caerulein-induced acute pancreatitis." (PMID 34830018, 2021). "This suggests that MAdCAM-1 might play a role in the recruitment of lymphocytes, resulting in the exacerbation of both local injury and remote injury to multiple organs in acute pancreatitis." (PMID 34830018, 2021).
Autoimmunity (1 paper, 2019). The occurrence of an immune reaction against the organism's own cells or tissues. "In summary, our data suggest a MAdCAM-1-associated modulation of CNS autoimmunity within the intestinal tract and add new insight into a functional role of the intestine in neuroinflammation." (PMID 31114574, 2019). "To further examine the effect of MAdCAM-1 on cellular events that drive CNS autoimmunity, we analyzed CNS infiltrating immune cells at the maximum of active EAE by ex vivo flow cytometry." (PMID 31114574, 2019). "This prompted us to investigate the role of MAdCAM-1 in immunological processes in the intestine during T cell-mediated autoimmunity of the central nervous system (CNS)." (PMID 31114574, 2019). "Therefore, in the present study, we focus on the role of MAdCAM-1 in the development of T cell-mediated autoimmunity by inducing active MOG35−55 –EAE in MAdCAM-1-KO mice." (PMID 31114574, 2019).
breast carcinoma (1 paper, 2020). "For example, the increased expression of ATOX1 and MADCAM1 in MDA-MB-231 breast cancer cells corresponded with their promoter hypomethylation in canine DCIS and invasive cancer samples." (PMID 32051475, 2020).
celiac disease (1 paper, 2014). An autoimmune genetic disorder with an unknown pattern of inheritance that primarily affects the digestive tract. "MAdCAM-1 has been shown to be is significantly upregulated in treatment naïve patients with celiac disease." (PMID 25705619, 2014). "For migration of lymphocyte to the site of inflammation (intestinal mucosa in case of celiac disease), T cells express integrin (α4β7), which are required for their binding to mucosal addressin cell adhesion molecule-1 (MAdCAM-1) located on vascular endothelial cells." (PMID 25705619, 2014). "Therefore, lymphocytic recruitment blockade using blockers of integrin (α4β7 and MAdCAM-1) could be a potential therapeutic target for patients with celiac disease." (PMID 25705619, 2014).
cerebral amyloid angiopathy (1 paper, 2020). "Of note, the top three MAdCAM-1 expression values correspond to B3 subjects with concomitant cerebral amyloid angiopathy (CAA) and general cerebrovascular disease (CVD)." (PMID 33041998, 2020).
dyslipidemia (1 paper, 2021). "MAdCAM-1 cannot serve as a marker of disease activity, dyslipidemia, or liver pathology in PSO, but it might play a role as an inflammation indicator." (PMID 34827121, 2021).